ANXA9 (annexin A9)
Diseases named in the same sentence as ANXA9 in open-access papers (continued):
Sharing a sentence is not in itself a finding about the gene and the disease.
cancer (11 papers, 2016 to 2025). A tumor composed of atypical neoplastic, often pleomorphic cells that invade other tissues. "Analyzing TCGA data, we observed that elevated ANXA9 levels were associated with poor outcomes in several cancers." (PMID 40427072, 2025). "ANXA9 dysfunctions have been reported in several human cancers, showing a protumor role mainly linked to invasion and metastasis processes." (PMID 36247003, 2022). "Among the top candidates, ANXA9 emerged as a significantly overexpressed gene in chemoresistant tumors, and its expression correlated with a poor prognosis across multiple cancer types." (PMID 40427072, 2025). "To investigate the mechanism behind ANXA9’s ability to transfer the S100A4 out of cancer cells, we treated BC cells with okadaic acid (a phosphatase inhibitor) to increase ANXA9 phosphorylation." (PMID 38609357, 2024). "Taken together, these data indicate that ANXA9 is highly expressed in different races, ages, cancer stages, node metastasis stages, and menopause status of BCA patients relative to the normal group." (PMID 37294149, 2023). "Emerging evidence has revealed that Annexin A‐9 (ANXA9) plays a crucial function in the development of some cancers." (PMID 37294149, 2023). "In the present study, the TIMER database revealed that ANXA9 was highly expressed in various cancer types, including BCA." (PMID 37294149, 2023). "Then, we expanded our research to explore the link between ANXA9 expression and cancer prognosis." (PMID 40427072, 2025). "Few studies have analyzed the expression of ANXA9 in cancers." (PMID 33680718, 2021). "Additionally, we found that ANXA9 could transfer the S100A4 out of cancer cells and down regulation of ANXA9 could decreased the cytokines of IL-6, IL-8, CCL2, and CCL5." (PMID 38609357, 2024). "Interestingly, we also noticed low ANXA9 expression in various cancers (p ˃ 0.05)." (PMID 37294149, 2023). "ANXA9 belongs to the ANXA group and its regulatory role has also been explored in some cancer types." (PMID 37294149, 2023). "The UALCAN database showed that ANXA9 dysregulation is found in BCA cancer patients with different races, ages, clinical stages, cancer subtypes, node metastasis status, and menopause status." (PMID 37294149, 2023). "Nevertheless in the few studies performed related to the effect of ANXA9 and ANXA13 in tumour demonstrated ANXA9 and ANXA13 could promote invasion and metastasis in a certain types of cancers." (PMID 37464398, 2023). "Interestingly, 5 out of the top 10 hub genes in the network are cancer genes, including ELF3, SLC10A4, ANXA9, DEFB118, KRT8." (PMID 32064261, 2020).
tumor (10 papers, 2014 to 2025). "We observed that a higher positivity rate of ANXA9 expression was associated with a greater tumor infiltration depth and a higher incidence of lymphatic metastasis in CRC tissue samples." (PMID 40427072, 2025). "In tumor cells, the expression is mainly membranous, similar to that observed for ANXA2 and the expression of ANXA9 is mainly associated with the degree of differentiation of the tumor, with higher expression in well differentiated cases." (PMID 30744186, 2019). "According to this network, we found that the exosome markers CD81, CD9, CD63, and TSG101 were associated with ANXA9, suggesting that ANXA9 may exist in exosomes in tumor tissues." (PMID 37294149, 2023). "G749 treatment resulted in a significantly enhanced anti-tumor effect, as demonstrated by a marked reduction in Ki-67 and ANXA9 expression levels, assessed through immunohistochemistry (IHC) analysis." (PMID 40427072, 2025). "Our study demonstrates that ANXA9 levels are significantly elevated in CRC tumor tissues compared to normal tissues." (PMID 40427072, 2025). "Our results provide compelling evidence that ANXA9 overexpression contributes to oxaliplatin resistance and tumor aggressiveness in CRC." (PMID 40427072, 2025). "Tumor size was significantly reduced (nearly half) in the LV‐sh‐ANXA9 group relative to the LV‐NC group in the xenograft model (p < 0.01), suggesting that ANXA9 silencing repressed tumor progression in BCA progression in vitro and in vivo." (PMID 37294149, 2023). "Subsequently, tumor volume and weight were also found to be significantly reduced in mice injected with LV‐sh‐ANXA9 (p < 0.05)." (PMID 37294149, 2023). "Among these, ANXA9 expression in tumor tissues of Caucasian BCA patients was the highest, followed by Asian BCA patients, and then the African American BCA patients." (PMID 37294149, 2023). "In the tumor‐bearing mouse models, ANXA9 expression in the LV‐sh‐ANXA9 group was lower than the control group (p < 0.05)." (PMID 37294149, 2023). "In another study, ANXA9 was shown to be involved in bone metastasis and was related to tumor relapse." (PMID 37294149, 2023). "ANXA9 mRNA and protein levels were upregulated in tumor tissues in contrast to adjacent non‐tumor tissues (p < 0.05)." (PMID 37294149, 2023). "ANXA9 expression in tumor tissues of BCA patients aged 61–80 years was markedly higher than patients aged 21–40 or 41–60 years (p < 0.05), suggesting ANXA9 expression gradually increased with the age of BCA patients." (PMID 37294149, 2023). "The expression levels of ANXA2, ANXA3, ANXA4, ANXA8, and ANXA9 were significantly increased in tumor tissues compared with normal tissues." (PMID 34484309, 2021). "Immunohistochemical analysis of ANXA9 expression was successfully evaluated in 346 of 372 tumor samples." (PMID 30744186, 2019). "Patients with values >1 (ANXA9 expression level in the tumor tissue was larger than that of the corresponding normal tissue) were assigned to the high expression group and the others were assigned to the low expression group." (PMID 25289111, 2014). "In the following analyses, ANXA9 expression normalized by GAPDH expression in the tumor tissue was calculated following division by ANXA9 expression level in the normal tissue." (PMID 25289111, 2014). "The expression of VEGFA in the xenograft tumor also revealed that sh-ANXA9 and sh-S100A4 could decrease it." (PMID 38609357, 2024). "The expression of VEGFA in the xenograft tumor also revealed that sh-ANXA9 and sh-S100A4 could decrease the expression of VEGFA." (PMID 38609357, 2024). "Similarly, biological assays further confirmed that ANXA9 mRNA and ANXA9 protein were notably overexpressed in tumor tissues of BCA patients and also in BCA cells, such as MCF7, SK‐BR‐3, and T‐47D cells." (PMID 37294149, 2023). "A tumor xenograft in vivo model was utilized to assess the role of ANXA9 in tumor growth in mice." (PMID 37294149, 2023).
tumor (continued). "Thus, we confirmed that ANXA9 was secreted by BCA tissue‐derived exosomes that function as a tumor promoter in BCA." (PMID 37294149, 2023). "Another study suggested that ANXA9 might promote the invasion and metastasis of CRC by regulating genes associated with tumor invasion and metastasis." (PMID 33680718, 2021). "This suggests that tumor malignancy correlates with ANXA9 expression and that this may also affect the values of other prognostic factors in multivariate analysis, such as distant metastasis, which was significant in the univariate analysis." (PMID 25289111, 2014). "ANXA9 expression was calculated as ANXA9/GAPDH expression for each tumor or normal tissue sample." (PMID 25289111, 2014). "Overall, ANXA9 silencing reduces cell proliferative, migratory, and invasive capabilities in vitro and reduces BCA tumor progression in vivo." (PMID 37294149, 2023). "Taken together, this study demonstrates that exosome‐derived ANXA9 is highly expressed in BCA patients and functions as a tumor promoter to facilitate proliferation, migration, and invasion and decrease cell apoptosis." (PMID 37294149, 2023). "Immunohistochemistry (IHC) staining revealed that ANXA9 expression was high in tumor tissues compared to the adjacent nontumor tissues." (PMID 37294149, 2023). "Although the present study highlights the tumorigenic role of ANXA9 in BCA progression, we did not examine the molecular mechanisms through which ANXA9 regulates tumor development; these are under investigation." (PMID 37294149, 2023). "In addition, possible correlations between ANXA9 and ANXA10 mRNA expression and the tumor grade were assessed using a homogeneous cohort of 243 HPV-negative HNSCC patients." (PMID 30744186, 2019). "In conclusion, exosome‐derived ANXA9 functions as an oncogene that facilitates the proliferation, migration, and invasiveness of BCA cells and enhances tumor growth in BCA development, which may provide a new prognostic and therapeutic biomarker for BCA patients." (PMID 37294149, 2023). "ANXA9 was highly expressed in BCA tumor tissues compared with normal tissues (p < 0.05)." (PMID 37294149, 2023). "However, in our report, we demonstrated that the expression of ANXA9 and ANXA11 in KIRC tissues was lower than that in normal tissues, and the expression did not correlate with tumour stage." (PMID 39290334, 2022).
digestive system tumors (2 papers, 2024 to 2025). "While ANXA9 has been previously linked to metastasis and immune infiltration in gastrointestinal tumors, its specific role in chemoresistance in CRC had not been clearly defined." (PMID 40427072, 2025). "There are few studies reports on ANXA9, with most studies focusing on digestive system tumors." (PMID 38609357, 2024).
ANXA9 also shares sentences with these, for which no sentence is quoted: Anxiety (1 paper); bone metastasis (1); cervical cancer (1); cholangiocarcinoma (1); colon adenocarcinoma (1); glioma (1); head and neck carcinoma (1); invasive breast carcinoma (1); kidney cancer (1); lung adenocarcinoma (1); lung squamous cell carcinoma (1); pancreatic cancer (1); pancreatic ductal adenocarcinoma (1); pemphigus (1); rectum adenocarcinoma (1); skin cutaneous melanoma (1); stomach adenocarcinoma (1).